TCF4 (transcription factor 4)
Diseases named in the same sentence as TCF4 in open-access papers (continued):
Sharing a sentence is not in itself a finding about the gene and the disease.
tumor (continued). "Transcriptional modulator TCF4/β-catenin complex and histone trimethylation complex PRC2 repressed miR-145 simultaneously, initiated the negative feedback loops and promoted tumor progression." (PMID 32195190, 2020). "Furthermore, in the present study, we did not observe any correlation of TCF-4 protein expression with clinicopathological factors such as age, sex and stage of the disease while a significant correlation of protein expression levels was observed with tumor grade (p = 0.029)." (PMID 32265994, 2020). "Finally, we demonstrated that HCT116 cells expressing dominant negative TCF4 (dnTCF4) or HCT116 cells with silenced Snail failed to stimulate IL1β production in macrophages, demonstrating that tumor cells activate macrophages via a Wnt-dependent factor." (PMID 23029025, 2012).
cancer (173 papers, 2007 to 2026). A tumor composed of atypical neoplastic, often pleomorphic cells that invade other tissues. "It inhibited the Wnt/β-catenin pathway abrogating the association of β-catenin with TCF-4 and the multidrug-resistant P-gp-expressing cancer cells." (PMID 41739665, 2026). "TCF4, a multifaceted transcription factor, is implicated in an array of processes including development, differentiation, neurodevelopment, and cancer." (PMID 39499704, 2024). "TNIK has garnered attention as a key regulator within the β-catenin and T-cell factor-4 (TCF-4) transcriptional complex which is a critical signaling pathway implicated in cancer development and progression." (PMID 39011472, 2024). "The present study investigated the role of E twenty-six variant transcription factor 4 (ETV4) among different cancers via pan-cancer analysis." (PMID 37205199, 2023). "In intestine cells, TRIB3 interacts with β-catenin and TCF4 to increase the expression of genes associated with cancer stem cells and promote CRC tumorigenesis." (PMID 35610288, 2022). "This study also suggests that investigating TCF4 functions and regulatory mechanisms in cancers must account for the complexity caused by multiple isoforms." (PMID 36116131, 2022). "A mutation in TCF4 was found de novo in all treatments, and analysis of drug sensitivity profiles across cancer cell lines supported the link to chemoresistance." (PMID 29666142, 2018). "TCF4 encodes transcription factor 4, and is closely related to the canonical Wnt pathway, which plays key roles in development, tissue homeostasis, and cancer." (PMID 28099906, 2017). "The next important step will be to determine if, in vivo, aspirin results in differential binding of TCF4 in regulatory sites adjacent to key cancer-associated genes such as 8q24 within colonic epithelium." (PMID 28143522, 2017). "We note that known EMT drivers ZEB1, SNAI2, and TCF4 in module 5 have significant associations with survival in our pan-cancer analysis (p values 8.5 × 10–6, 5.3 × 10–4, 1.3 × 10–3 and rankings 153, 749, and 1098, respectively, out of 11,119 total genes)." (PMID 27287041, 2016). "T-cell factor 4 (TCF-4) has been shown to exhibit abnormal mutations in various types of cancer." (PMID 39735605, 2024). "Since the APCDD1 gene has been linked to CRC by being involved in the Wnt signaling pathway as a direct target of the beta-Catenin/TCF4 complex, the associated variant (p.R299H) was prioritized as the top cancer-predisposing candidate of all identified missense variants." (PMID 33673279, 2021). "Numerous studies have also implicated TCF4 in cancer progression." (PMID 34021255, 2021). "Nonetheless, studies of larger series with pre- and post-chemotherapy cancer samples may be warranted to decipher the precise mechanism by which altered TCF4 function is linked to chemoresistance." (PMID 29666142, 2018). "Therefore, the invasive phenotype induced by inflammatory media from macrophages implicated the activation of the β-catenin/TCF4 transcriptional pathway in at least some cancer cells." (PMID 29462209, 2018). "Silencing of Tcf4 causes a significant sensitization of cancer cells to low doses of radiation." (PMID 27014877, 2016). "Additionally, TCF4 has been found to be associated with tumorigenesis in a variety of tumors and was a potential molecular target against kinds of cancer, suggesting that TCF4 may be an intervention target for the subgroup 3." (PMID 34671197, 2021). "Therefore, we investigated whether integrin β1/AKT/GSK-3β/β-catenin/TCF4/Nanog signal pathway was implicated in POSTN promoting cancer stem phenotypes of heat-exposed residual HCC cells." (PMID 28526827, 2017). "Module 5 contains known EMT inducers ZEB1, SNAI2, and TCF4 (E2.2), as well as multiple other genes known to be important in focal adhesion, extracellular matrix interaction, extracellular matrix organization, and markers of cancer-associated fibroblasts (PDGFRB, PDGFRA)." (PMID 27287041, 2016).
cancer (continued). "Because TCF4 has been shown to be constitutively activated by mutated β-catenin and the induction of the pro-apoptotic pathway directly leads to the reduction of TCF4 mRNA and protein levels, TCF4 could be a therapeutic target for anti-cancer drugs." (PMID 25961950, 2015). "For example, looping between the c-MYC promoter and an enhancer that contains a cancer-associated SNP, rs6983267, was shown to occur equally in both alleles, and the phenotype is thought to be driven by an increase in enhancer activity due to differential transcription factor 4 (TCF4) binding." (PMID 26632825, 2015). "Though class I bHLH TFs (TCF3, TCF4, and TCF12) are important for cancer, development, and immunity, and associated with neural disorders, how they functionally contribute to these processes is poorly understood." (PMID 39119816, 2025). "Wnt/β‐catenin blockade by specific inhibitors or TCF4 knockdown was found to sensitize cancer stem cells to elesclomol–Cuprum‐induced cuproptosis." (PMID 41163302, 2025). "In CRC, the expression of JUN was reported to be upregulated and play an important role in the cancer progression by making a complex with the TCF4 and β‐catenin (CTNNB1) transcription factors." (PMID 38872418, 2024). "Recently, it has been reported that TERT interacts with various signaling molecules such as NF-κ B, c-MYC, β-catenin, and TCF-4 to increase cancer malignancy and promote cancer progression." (PMID 38927493, 2024). "Nuclear β-catenin and TCF4 synergistically promote the upregulation of cancer stem cell-like properties." (PMID 38714724, 2024). "Some report also shows that Emodin can suppress the PTHLH expression in related cancer by suppressing the TCF4/TWIST1‐induced complex." (PMID 37555363, 2023). "Mutational activation of Wnt signalling aberrantly transactivates downstream TCF4/beta-catenin target genes, further contributing to malignant transformation in human cancers." (PMID 36854722, 2023). "The ultimate aim of the typical Wnt signalling in the beta-catenin pathway is the formation of the TCF4/beta-catenin complex, and this interaction is regarded as a valid target for cancer treatment." (PMID 36854722, 2023). "The aberrant proliferation of cancer cells is due to the disruption of T cell factor-4 (TCF-4)-stimulated Wnt/β-catenin signaling pathway." (PMID 34617205, 2022). "TCF4N is a predicted target for the inhibition of tumourigenesis and for progression in cancers, operating by disrupting the interaction between β‐catenin and TCF4." (PMID 36116131, 2022). "Although there are few studies on the details of TDCPP exposure and TCF4 expression, there are notable functional connections to cancer progression and its downstream networks." (PMID 35304560, 2022). "Our research of β-catenin pathways in HBL patients revealed that the β-catenin-TCF4-CEGRs/ALCDs pathway accelerates the proliferation of cancer cells and increases the expression of many oncogenes, including AFP and GPC3." (PMID 36551548, 2022). "Dysregulated expression of TCF4 has been demonstrated in several human cancers and implies autoimmune diabetes." (PMID 34576267, 2021). "PHGDH is overexpressed in many cancers, either via gene copy-number gain, or transcriptional upregulation mediated via activation of transcription factor 4 (ATF4)." (PMID 33397437, 2021). "The repression of miR-181 by CRNDE determined the higher expression of CTNNB1 and transcription factor 4 (TCF4) miR targets with a promotion of cancer cell growth, 5-FU and L-OHP resistance in CRC cells." (PMID 34503164, 2021). "Blockade of TCF4/Wnt pathway using a small molecule antagonist suppress the proliferation of the cancer cells in vivo and vitro through targeting c‐Myc, cyclin D1 and surviving." (PMID 33951279, 2021). "According to other authors, TDG interacts with transcription factor TCF4 and acts as a positive regulator in the Wnt pathway, is upregulated in human cancer and is required for cancer growth." (PMID 32140249, 2020).
cancer (continued). "Increased protein abundance of Wnt signaling effectors, such as β-catenin and TCF4, due to the deregulation of protein translation, has also been observed in various cancers." (PMID 32824859, 2020). "We divided TFs into three categories: the first one is represented by TFs whose splice variants affect the cancer cell phenotype by regulating different classes of genes (NF-YA, STAT3, TCF4 and WT1)." (PMID 32244895, 2020). "Such being the case, Wnt5A, CTNNB1P1, SMAD4, and TCF4 was expressed primarily in the para-cancer tissues but were reduced to varying degrees in cancer tissues." (PMID 32273945, 2020). "Relatively, FZD10 and TCF4 were highly expressed in these para-carcinoma tissues but significantly reduced in the core carcinoma tissues." (PMID 32273945, 2020). "Previous studies investigating β-catenin/TCF-4 with in relation to various cancers have indicated its potential as a treatment target option for a variety of cancers including NPC." (PMID 30867651, 2019). "We herein report that the molecular mechanisms of NRF3 induction in cancer cells involve the β-catenin/TCF4 complex." (PMID 31288376, 2019). "The β-catenin/TCF4 complex mediates NRF3 expression in several cancer cells through binding to its WRE site." (PMID 31288376, 2019). "The difference in staining intensities (measured by H-score) of β-catenin and TCF4 between normal and carcinoma samples (represented by Notched Box Plot) were extremely statistically significant, as predicted by the Mann–Whitney U-test analysis." (PMID 31351496, 2019). "Staining intensities of β-catenin, TCF4 and RelA (measured by H-score) followed similar trends in both normal and carcinoma samples." (PMID 31351496, 2019). "An interesting finding identified the hyper-activation or aberrant activation of β-catenin/TCF-4 as one of the most common abnormalities of signaling in multiple kinds of carcinomas." (PMID 30867651, 2019). "Many studies have demonstrated that the β-catenin/TCF4 pathway plays a critical role in regulating cancer cell proliferation." (PMID 30249289, 2018). "To test this idea, we used dominant negative (DN)-TCF4 to inhibit Wnt signaling in both normal and cancer cells, and compared the effect on cell growth." (PMID 28570681, 2017). "Nevertheless, the specific disruption of the interaction between nuclear β-catenin and Tcf4 following selective radiation treatment represents a particularly promising strategy for preventing the proliferation and survival of cancer cells." (PMID 27014877, 2016). "As expected, hypoxic exposure significantly increased cancer stemness related factors (c-Myc, Klf4, Nanog, and Oct4) and Wnt/β-catenin signaling components (Wnt1, TCF4, and Cyclin D1)." (PMID 26965643, 2016). "The 95 % confidence intervals of the hazard ratios of P4HA3, SRPX2, DCN, OMD, and TCF4 all excluded 1 in multivariate analysis in both cancer sets." (PMID 27809802, 2016). "We also analyzed TCF4, which was found in the positive prognosis set, and FAP, a marker for cancer associated fibroblasts." (PMID 27809802, 2016). "This pathway is over-activated in NSCLC and many other cancers due to overexpression of Tcf4, Wnt1, and Wnt2 and leads to an elevated accumulation of β-catenin in nuclei." (PMID 27014877, 2016). "Despite its significant role in transcriptional activation and repression, the role of TCF4 in cancer prevention has remained poorly understood." (PMID 25961950, 2015). "The identification of signaling components that are involved in TCF4 phosphorylation and proteasomal degradation in response to phytochemicals will assist in our understanding of Wnt signaling processes coordinating cancer development." (PMID 25961950, 2015). "To address this issue, we first examined the expression of β-catenin, TCF4 and p68 in various established cancer cell lines and HEK293T cells." (PMID 25499975, 2014). "To examine this, we have selected MCF7 cells where both TCF4 and p68 expressions are low compared to other cancer cell lines." (PMID 25499975, 2014).
cancer (continued). "Slug (Snail-2) is E-cadherin transcriptional repressor that, together with Snail-1 promotes formation of β-Catenin/TCF4/LEF-1 transcription complexes that initiate EMT in different types of cancers." (PMID 25215932, 2014). "The results indicate that there is a probable correlation for β-catenin and TCF4 with p68 in the cancer cell lines." (PMID 25499975, 2014). "Here, we propose a model indicating regulation of p68 gene expression in cancer cells by Wnt signaling through a positive feedback mechanism involving β-catenin and TCF4." (PMID 25499975, 2014). "The GL treatment resulted in a significant reduction of β-Catenin /TCF-4 complex in both of the cancer cells." (PMID 23914993, 2013). "The same treatment, however, can exert a ∼ 95% inhibition of the β-Catenin binding to TCF-4 in both cancer cells." (PMID 23914993, 2013). "As reported by others, WNT5A, LBH, WISP1 and TCF4 were expressed at lower levels in ER+ cell lines compared to ER-ve cancer but also compared to immortalised normal breast cell lines, perhaps reflecting their ER-ve status." (PMID 23861811, 2013). "The β-catenin/Tcf-4 pathway is an important signaling pathway that tips the balance of cell proliferation and apoptosis in cancer cells." (PMID 23029137, 2012). "The constitutive presence of TCF4/β-catenin complexes locks the Wnt transcriptional program, normally active only in crypt stem cells and progenitors, in the “on” state, resulting in malignancies in the gut." (PMID 21103407, 2010). "Furthermore when correlating both factors with survival we found that only TCF4 expression was associated with a significant lower overall survival, which fits with the continuous activation of the Wnt/β-catenin signalling pathway in colorectal tumorigenesis and malignant tumour progression." (PMID 21092222, 2010). "Moreover, we found that TCF4 has the highest expression in NB of all cancer types found in the Cancer Cell line Encyclopedia (CCLE) database." (PMID 39119816, 2025). "Given lower b-catenin levels in serrated pathway CRCs compared to APC-mutant carcinomas, TCF4 overexpression could efficiently drive WNT activation in a manner that is favorable to these tumors." (PMID 40687798, 2025). "Furthermore, we provided evidence for the potential anti-cancer application of MESP2 as a marker for targeted therapy involving TCF4/beta-catenin signalling." (PMID 36854722, 2023). "Notably, LBH upregulation in CRC, PAAD, ESCA, and STAD cancer lines coincided with both, increased β-catenin and TCF4 protein expression, as well as increased TOPFlash reporter activity, a measurement of β-catenin/TCF transcriptional activity." (PMID 37268816, 2023). "Based on these results, we present a new hypothesis that TCF4/beta-catenin signalling is controlled inhibited by MESP2, but becomes significantly activated in the carcinoma stage due to MESP2 loss." (PMID 36854722, 2023). "Previous studies have reported that TCF4 regulates cancer development and progression." (PMID 35406121, 2022). "Moreover, we identified ITF2/TCF4, a basic helix‐loop‐helix TF, which is induced by Wnt/β‐catenin to promote cancer growth, as upstream regulator of GPR56, suggesting positive feedback between GPR56 and Wnt." (PMID 35253392, 2022). "TCF4, as an important regulator of epithelial-mesenchymal transition and downstream of the Wnt/β-catenin signaling pathway, has been reported to be involved in cancer metastasis." (PMID 35125116, 2022). "TGFβ1 signalling upregulates TCF4 expression in cancer cells." (PMID 35406121, 2022). "In cancer prevention and therapy, the regulation of β-catenin/Tcf4 signaling to reduce abnormal cell proliferation with active components could be a potential strategy." (PMID 34976156, 2022).